TLR10 (toll like receptor 10)
Diseases named in the same sentence as TLR10 in open-access papers (continued):
Sharing a sentence is not in itself a finding about the gene and the disease.
cervical cancer (3 papers, 2020 to 2024). A primary or metastatic malignant neoplasm involving the cervix. "Among the diversity of receptors, TLR10 is the most recently described, generating controversy regarding its function; TLR4 recognizes exogenous pathogens and is closely linked to the growth of HPV-positive cervical cancer." (PMID 39208235, 2024). "In addition, the TLR9, TLR10, and TLR5 cascades were associated with the DE genes in our study, and they were similarly dysregulated in HPV infection and cervical cancer progression." (PMID 32151264, 2020). "When evaluating the gene expression patterns of TLR transcripts, specifically TLR1, TLR3, TLR4, TLR6, TLR7, TLR8 and TLR10, in HPV+ and HPV- cervical cancer tissue samples, we observed an increase in TLR4 expression and a decrease in TLR1 and TLR3 expression." (PMID 39208235, 2024). "To validate the expressions of IGSF6, TLR10, FCRL3, and IFI30 in cervical cancer, we performed immunohistochemistry against these genes, respectively." (PMID 36387234, 2022). "Consistently, the expressions of IGSF6, TLR10, FCRL3, and IFI30 were upregulated in cervical cancer in the validation cohort." (PMID 36387234, 2022). "Apart from this, an intriguing notion is that the four genes (IGSF6, TLR10, FCRL3, and IFI30) were also upregulated in cervical cancer compared to normal tissues, while their high expressions predicted better prognosis." (PMID 36387234, 2022). "By univariant Cox and LASSO analyses, we finally got 4 genes (IGSF6, TLR10, FCRL3, and IFI30) that were closely correlated with both the CD8+ T cell infiltration and the prognosis of cervical cancer." (PMID 36387234, 2022). "Based on these facts, we thought that the discovery of the 4 novel genes (IGSF6, TLR10, FCRL3, and IFI30) in cervical cancer might shed light on the clinical treatments of cervical cancer as well." (PMID 36387234, 2022). "As the expressions of IGSF6, TLR10, FCRL3, and IFI30 were all upregulated in cervical cancer and the higher expressions of IGSF6, FCRL3, and IFI30 predicted better prognosis, we asked if the combination of these four genes was associated with the risks of cervical cancer." (PMID 36387234, 2022). "To validate the immune infiltration pattern, the expressions of IGSF6, TLR10, FCRL3, and IFI30, and the correlation between them, we downloaded the GSE151666 dataset from the GEO database as a validation cohort, which included 68 cervical cancer patients." (PMID 36387234, 2022). "In line with the results from the transcriptomics, we identified stronger expressions of IGSF6, TLR10, FCRL3, and IFI30 in cervical cancer tissues compared to normal tissues." (PMID 36387234, 2022).
COVID-19 (3 papers, 2022 to 2025). A disease caused by infection with severe acute respiratory syndrome coronavirus 2. "Our results suggest that the TLR10 variant rs149895872 may contribute to the response to corticoid and immunomodulator treatments in COVID-19 patients." (PMID 40149530, 2025). "Our results suggest that the TLR1, TLR4, TLR6, and TLR10 variants may influence the outcome during corticoid treatment in COVID-19 patients." (PMID 40149530, 2025). "With the ability to suppress the expression of proinflammatory cytokines and chemokines, regulation of TLR10 may be a promising approach to balance the inflammatory response in respiratory diseases, including in severe cases of COVID-19, in which a cytokine storm can cause organ damage." (PMID 36671404, 2022). "Harnessing the immunomodulatory effects of TLR10 could have potential therapeutic applications for the treatment of patients with severe COVID-19 as well as for the management of other inflammatory diseases." (PMID 39902041, 2024).
influenza infection (3 papers, 2014 to 2019). "Recent evidence shows that TLR10 plays a key role in the innate immune response following an influenza infection." (PMID 30930906, 2019). "TLR10 has recently been shown to play a role in innate immune response in influenza infection and that its expression is stronger during infection by the highly pathogenic influenza H5N1 virus." (PMID 25365328, 2014). "Moreover, TLR10 has been shown to be involved in osteoarthritis, Crimean Congo hemorrhagic fever, Listeria monocytogenes, Salmonella Typhimurium, Helicobacter pylori, and influenza." (PMID 30930906, 2019).
Obesity (3 papers, 2019 to 2024). Accumulation of substantial excess body fat. "In human adipose tissue, individuals with TLR10 gene polymorphisms were proved to exhibit a reduced infiltration of macrophage in obese individuals and may result in the TLR10-induced inhibition of inflammation during obesity." (PMID 38989000, 2024). "More studies need to assess the value of TLR10 as a therapeutic target in obesity and metabolic syndrome." (PMID 31582899, 2019). "A recent study indicated that TLR10 impacts adipose tissue morphology in obesity." (PMID 31582899, 2019). "Multiple TLRs, including TLR2, TLR3, TLR4, TLR5, TLR8, TLR9, and TLR10, have been indicated in the regulation of PAMPs from gut microbiota and DAMPs from metabolic stress and tissue damage, which initiate the inflammatory responses contributing to the development of obesity-related chronic diseases." (PMID 31582899, 2019).
rheumatoid arthritis (3 papers, 2016 to 2019). A chronic, systemic autoimmune disorder characterized by inflammation in the synovial membranes and articular surfaces. "Nonetheless, the clinical significance of TLR10 in rheumatoid arthritis (RA) remains unclear." (PMID 30686934, 2018). "TLR10 has been poorly studied in chronic inflammatory disorders, and its clinical relevance in rheumatoid arthritis (RA) is as yet unknown." (PMID 27716427, 2016).
allergic disease (2 papers, 2017). An immune response that occurs following re-exposure to an innocuous antigen, and that requires the presence of existing antibodies against that antigen. "In addition, SNPs in this region have previously been associated with altered expression of the TLR10 gene, suggesting that altered gene expression of TLR10 may be involved in the pathogenesis of allergic disease." (PMID 28228119, 2017).
autoimmune disease (2 papers, 2018 to 2024). A disorder resulting from loss of function or tissue destruction of an organ or multiple organs, arising from humoral or cellular immune responses of the individual to their own tissue constituents. "Additionally, novel therapeutic applications are being developed for TLR10 due to its unique anti-inflammatory properties, suggesting its potential use in therapeutics targeting inflammatory and autoimmune diseases." (PMID 38732254, 2024).
gastric cancer (2 papers, 2015 to 2019). A primary or metastatic malignant neoplasm involving the stomach. "TLR1 and TLR10 gene polymorphisms were associated with a higher risk for gastric cancer in H. pylori-infected individuals." (PMID 30863783, 2019). "A recent study proved that TLR1 rs4833095 and TLR10 rs10004195 gene polymorphisms are associated with a higher risk of gastric cancer in H. pylori-infected individuals." (PMID 30863783, 2019).
hearing loss (2 papers, 2019 to 2022). "The allelic variant may associate with the progression of hearing loss in patients with MD, such as major histocompatibility complex class I chain-related A (MICA) and Toll Like Receptor 10 (TLR10)." (PMID 35683514, 2022).
Insulin resistance (2 papers, 2022 to 2023). Increased resistance towards insulin, that is, diminished effectiveness of insulin in reducing blood glucose levels. "• T cell activation. • Induction of inflammatory molecules like IL8, IL12A, CCL5, CCL19, CCR2, and CCR5. • Contribution to increased insulin resistance secondary to TLR2, TLR4, and TLR10 interaction." (PMID 35422689, 2022).
leukemia (2 papers, 2021 to 2024). A malignant (clonal) hematologic disorder, involving hematopoietic stem cells and characterized by the presence of primitive or atypical myeloid or lymphoid cells in the bone marrow and the blood. "In the co-culture experiment, we investigated whether overexpression of TLR10 in immunostimulated A549 cells affects gene expression in the monocytic human leukemia cell line THP-1." (PMID 39902041, 2024).
lung carcinoma (2 papers, 2021 to 2022). "Therefore, the expression regulation of signaling molecules, cytokines, and effectors that play important roles in the development of chronic lung inflammation and lung cancer by overexpression of endogenous TLR10 could have great therapeutic potential." (PMID 36671404, 2022). "To facilitate clinical application, in the lung cancer transcriptome, including 19,464 protein-coding genes, we extracted the three most relevant genes of B cell (CD19, TLR10, and FCRLA) and DC1 (ITGB2, LAPTM5, and SLC7A7), respectively." (PMID 34422829, 2021).
mastitis (2 papers, 2009 to 2015). Inflammation of breast tissue during lactation or postpartum due to an obstructed duct or infection. "However, TLR10 is not functional in mice and must therefore be excluded as a common candidate for both species, although it remains a possible candidate gene for the mastitis related QTL in cattle." (PMID 19432955, 2009).
abscesses (1 paper, 2020). "Strikingly, polymorphisms in TLR2 and TLR10 genes previously found to be associated with increased susceptibility to cSSSIs did not affect clinical severity as defined by lesion size in patients with major abscesses and DFIs in this study." (PMID 31786695, 2020).
adrenocortical tumors (1 paper, 2024). "Additionally, in the case of pituitary tumors, genes related to neuronal function, survival, and morphogenesis were repeatedly identified, while in patients with adrenocortical tumors, TLR10, which is involved in the regulation of the innate immunity, was commonly modified." (PMID 38256138, 2024).
Alzheimer ́s disease (1 paper, 2021). "While TLR2, TLR4, TLR5 and TLR10 might be involved in the pathogenesis of systemic sclerosis, TLR activation can have both destructive and protective effects on Alzheimer ́s disease (AD)." (PMID 33499143, 2021).
Autoimmunity (1 paper, 2019). The occurrence of an immune reaction against the organism's own cells or tissues. "The first evidence about the possible involvement of TLR10 in autoimmunity has been already observed: downregulated TLR10 expression was reported in PBMC of patients with microscopic polyangiitis as well as RA patients with active disease." (PMID 31396542, 2019).
Bartonella infection (1 paper, 2025). "In this study, we analyzed the polymorphisms in six cell surface TLR genes (TLR1, TLR2, TLR4, TLR5, TLR6, and TLR10) in striped hamsters, aiming to determine their association with Bartonella infections and ectoparasite parasitism, including fleas and gamasid mites." (PMID 40678527, 2025). "Notably, four key sites influencing Bartonella infection susceptibility were identified, with two on TLR1 and one each on TLR4 and TLR10." (PMID 40678527, 2025).
childhood asthma (1 paper, 2013). "Toll-like receptor 2, toll-like receptor 6, toll-like receptor 9, and toll-like receptor 10 appear to have some association with childhood asthma in Caucasians." (PMID 23496969, 2013).
coagulopathy (1 paper, 2025). "Coagulopathy, measured by INR, was associated with platelet-TLR4 and leukocyte-TLR10." (PMID 40825056, 2025). "Additionally, increased coagulopathy was associated with platelet-TLR4 and leukocyte-TLR10." (PMID 40825056, 2025). "Additionally, coagulopathy measured by INR, negatively correlated with TLR4 in platelets and TLR10 in leukocytes." (PMID 40825056, 2025).
colon adenocarcinoma (1 paper, 2023). "In another study, they silenced TLR10 in the human colon adenocarcinoma cell line HT-29 and in monocytic THP-1 cells, which led to increased viability of Listeria monocytogenes, and they unveiled that the heterodimer of TLR2/TLR10 was the one behind the activation of NF-κB." (PMID 37569837, 2023).
eczema (1 paper, 2022). "Both TLR1 and TLR10 have also been associated with AD and eczema in human GWAS79,80." (PMID 36482174, 2022).
endometriosis (1 paper, 2020). The growth of functional endometrial tissue in anatomic sites outside the uterine body. "TLR1, 5, 6, 7, 8 and TLR10 showed a significantly higher expression in endometriosis patients compared to the control (p<0.05)." (PMID 33209739, 2020).
glioma (1 paper, 2021). A benign or malignant brain and spinal cord tumor that arises from glial cells (astrocytes, oligodendrocytes, ependymal cells). "Up to date, TLR2, TLR3, TLR4, TLR7, and TLR9 have been intensely studied in glioma, while less or missing information is available regarding the mechanisms of TLR1/TLR6 (dimerizes with TLR2), TLR5, TLR8 (dimerizes with TLR7), and particularly TLR10." (PMID 34715891, 2021). "The impact of TLR3, TLR5, TLR7, TLR8, and TLR10 signaling in glioma development is not fully elucidated." (PMID 34715891, 2021). "Up to date, TLR7/8 expression was found absent in glioma cell lines (CNS-1 and GL-261), and TLR10 has unknown ligand and was poorly investigated." (PMID 34715891, 2021).
hypothyroidism (1 paper, 2022). Abnormally low levels of thyroid hormone. "As an example, the most significant pathway detected by PANTHER is a toll-like receptor signaling pathway for co-cluster 111 comprised of hypothyroidism/myxedema and levothyroxine sodium medication, and genes TLR1, TLR6, and TLR10 in the cells—EBV-transformed lymphocytes tissue." (PMID 35987940, 2022).
leptospirosis (1 paper, 2021). A contagious bacterial infection caused by spirochetes of the genus Leptospira. "Polymorphisms in TLR6 and TLR10 were more frequent in animals negative for leptospirosis, neosporosis, viral diarrhea, and leukosis, suggesting that this chromosome has candidate genes for resistance to infections." (PMID 34070451, 2021).
mantle cell lymphoma (1 paper, 2014). Mantle cell lymphoma is a rare form of malignant non-Hodgkin lymphoma affecting B lymphocytes in the lymph nodes in a region called the ``mantle zone''. "In mantle cell lymphoma (MCL), TLR1, TLR4, TLR7, TLR9 and TLR10 exhibit significant mRNA levels, whereas TLR2, TLR3, TLR5 and TLR8 are negative." (PMID 25112836, 2014).
ovarian carcinoma (1 paper, 2020). A malignant neoplasm originating from the surface ovarian epithelium. "We found that the expression level of TLR10 in ovarian cancer tissue was significantly higher than that in normal ovarian tissues." (PMID 32329191, 2020). "It is suggested that the expression of TLRs, TLR4, TLR9 and TLR10 was significantly reduced in the local macrophage‐infiltrating microenvironment of ovarian cancers." (PMID 32329191, 2020). "The expression levels of TLR4, TLR9 and TLR10 were significantly enhanced in the local macrophage‐infiltrating microenvironment of ovarian cancer." (PMID 32329191, 2020).
Parkinson disease (1 paper, 2021). A progressive degenerative disorder of the central nervous system characterized by loss of dopamine producing neurons in the substantia nigra and the presence of Lewy bodies in the substantia nigra and locus coeruleus. "TLR10 on peripheral blood monocytes reduces TLR2-induced cytokine production in Parkinson’s disease, which is also a co-receptor of TLR2." (PMID 35126357, 2021).
periodontal disease (1 paper, 2025). "The observed downregulation of TLR3 and TLR10 in inflamed PDLSCs suggests a shift from anti-inflammatory functions of the cells to a bacterially driven pro-inflammatory phenotype, which is characteristic of periodontal disease progression." (PMID 40136681, 2025).
periodontitis (1 paper, 2025). An acute or chronic inflammatory process that affects the tissues that surround and support the teeth. "Future research should explore therapeutic strategies to activate or mimic TLR10 function, investigating its role as a key modulator in preventing immune hyperresponsiveness in periodontitis." (PMID 40136681, 2025).
psoriasis (1 paper, 2021). An autoimmune condition characterized by red, well-delineated plaques with silvery scales that are usually on the extensor surfaces and scalp. "Real-time polymerase chain reaction (PCR) revealed that the expression levels of TLR3, TLR5, TLR6, TLR7, TLR9, and TLR10 in lesional skin were higher than those in peripheral blood mononuclear cells (PBMCs) of the same patients with psoriasis." (PMID 34790055, 2021).
vitiligo (1 paper, 2015). Generalized well circumscribed patches of leukoderma that are generally distributed over symmetric body locations and is due to autoimmune destruction of melanocytes. "Two other SNPs of TLR10 (rs10776482 and rs7660429) and one SNP located in 5′ direction from TLR10 (rs12233670) were associated in vitiligo subgroups." (PMID 26442097, 2015).